FEM1B (fem-1 homolog B)
Description:
Substrate-recognition component of a Cul2-RING (CRL2) E3 ubiquitin-protein ligase complex of the DesCEND (destruction via C-end degrons) pathway, which recognizes a C-degron located at the extreme C terminus of target proteins, leading to their ubiquitination and degradation. The C-degron recognized by the DesCEND pathway is usually a motif of less than ten residues and can be present in full-length proteins, truncated proteins or proteolytically cleaved forms. The CRL2(FEM1B) complex specifically recognizes proteins ending with -Gly-Leu-Asp-Arg, such as CDK5R1, leading to their ubiquitination and degradation. Also acts as a regulator of the reductive stress response by mediating ubiquitination of reduced FNIP1: in response to reductive stress, the CRL2(FEM1B) complex specifically recognizes a conserved Cys degron in FNIP1 when this degron is reduced, leading to FNIP1 degradation and subsequent activation of mitochondria to recalibrate reactive oxygen species (ROS) (By similarity). Mechanistically, recognizes and binds reduced FNIP1 through two interface zinc ions, which act as a molecular glue that recruit reduced FNIP1 to FEM1B (By similarity). Promotes ubiquitination of GLI1, suppressing GLI1 transcriptional activator activity. Promotes ubiquitination and degradation of ANKRD37 (By similarity). Promotes ubiquitination and degradation of SLBP. Involved in apoptosis by acting as a death receptor-associated protein that mediates apoptosis. Also involved in glucose homeostasis in pancreatic islet (By similarity). May also act as an adapter/mediator in replication stress-induced signaling that leads to the activation of CHEK1.
Synonyms: F1A-alpha; F1AA; FEM1-beta; NEDBES
Tractability: PROTAC: ubiquitination databases record sites on it; its protein half-life has been measured.
Gene: Protein-coding gene on chromosome 15 (68,277,745 to 68,295,862, forward strand). Ensembl gene ENSG00000169018.
Subcellular location: Cytoplasm; Nucleus
Subcellular location (Human Protein Atlas): Nucleoplasm; Cytosol
Pathways (Reactome):
Metabolism of proteins: Neddylation
Gene Ontology:
Molecular function: death receptor binding; protein binding; ubiquitin-like ligase-substrate adaptor activity
Biological process: proteasome-mediated ubiquitin-dependent protein catabolic process; regulation of DNA damage checkpoint; regulation of extrinsic apoptotic signaling pathway via death domain receptors; ubiquitin-dependent protein catabolic process via the C-end degron rule pathway; apoptotic process; protein ubiquitination
Cellular component: Cul2-RING ubiquitin ligase complex; cytoplasm; cytosol; mitochondrion; nucleoplasm; nucleus; ubiquitin ligase complex
Genetic constraint (gnomAD): Loss-of-function variants: 10 observed, 40.34 expected, observed/expected ratio (o/e) 0.25, 90% interval 0.15 to 0.42. The upper end of that interval is the gene's LOEUF score, 0.42, which puts it in group 1 of 6, group 1 being the genes least tolerant of losing a copy. Missense variants: 471 observed, 832.12 expected, observed/expected ratio (o/e) 0.57, 90% interval 0.52 to 0.61. Synonymous variants: 288 observed, 307.01 expected, observed/expected ratio (o/e) 0.94, 90% interval 0.85 to 1.03.
Homologues: Orthologues: chimpanzee FEM1B (100% identical), macaque FEM1B (100% identical), dog FEM1B (99% identical), pig FEM1B (99% identical), guinea pig FEM1B (99% identical), rat Fem1b (99% identical), mouse Fem1b (99% identical), rabbit FEM1B (92% identical), Drosophila melanogaster Fem-1 (41% identical), Caenorhabditis elegans fem-1 (29% identical). Paralogues in human: FEM1C (41% identical), FEM1A (39% identical), ANKRD33B (13% identical), ANKRD33 (10% identical).
Diseases named in the same sentence as FEM1B in open-access papers:
FEM1B is named in the same sentence as 22 diseases in open-access papers, as found by Europe PMC text mining. Sharing a sentence is not in itself a finding about the gene and the disease. The quoted sentences say what the papers report.
colon cancer (5 papers, 2015 to 2025). "In malignant colon cancer cells, it has been found that association of Rack1 with FEM1b mediates downregulation of FEM1b protein level by promoting ubiquitination of FEM1b8." (PMID 27644318, 2016). "RACK1 interacts with the apoptotic protein Fem1b to promote its ubiquitination level in colon cancer cells; downregulation of RACK1 leads to FEM1B‐mediated apoptosis." (PMID 39425259, 2025). "The Receptor for Activated C Kinase 1 (Rack1), a member of the tryptophan-aspartate repeat (WD-repeat) family proteins, was found to bind the N-terminus of Fem1b and poly-ubiquitinated Fem1b for proteasomal degradation in colon cancer cells." (PMID 27222660, 2016). "In apoptosis-resistant SW620 cell, derived from a primary colon cancer, Rack1 overexpression led to downregulation of FEM1b, an intracellular pro-apoptotic protein, by promoting its ubiquitination." (PMID 27644318, 2016). "Additionally, the protein Fem1b is found to be downregulated by the proteasome in malignant colon cancer cells, and Fem1b increases proteasome inhibitor-induced apoptosis of these cells." (PMID 27107416, 2016). "According to this research, FEM1b could represent a novel molecular target to overcome resistance to apoptosis in colon cancer." (PMID 27107416, 2016). "The proapoptotic protein FEM1b could represent a novel molecular target for overcoming apoptosis resistance in colon cancer therapy." (PMID 26448723, 2015). "In colon cancer cells, Rack1 inhibits apoptosis by directly interacting with FEM1 homolog b (FEM1b), an intracellular pro-apoptotic protein, and thus promoting its ubiquitination and degradation, while downregulation of Rack1 led to FEM1b-mediated apoptosis." (PMID 27644318, 2016).
breast carcinoma (2 papers, 2013 to 2024). "To confirm these observations in another cell line, we deleted a portion of the conserved region in the proximal 3′UTR of FEM1B in MDA-MB-231 cells (human breast cancer cells)." (PMID 39140134, 2024). "Consistent with the results of cell cycle analysis and the tumour xenograft experiments, there was a significant increase in the probability of survival in breast cancer patients with higher expression of FEM1B." (PMID 39140134, 2024). "Several studies have shown that FEM1B induces apoptosis when expression is increased in cancer cells, including breast cancer, cervical cancer, neuroblastoma, and fibrosarcoma cells." (PMID 23861741, 2013).
polycystic ovary syndrome (2 papers, 2019 to 2022). A disorder that manifests as multiple cysts on the ovaries. "Two genes, the fem-1 homolog B (FEM1B) and sperm equatorial segment protein 1 (SPESP1) on BTA10, were reported to be involved in polycystic ovary syndrome in humans and required for fully fertile sperm in mice, respectively." (PMID 35484513, 2022). "A functional variation (SNP rs10152450 and haplotype GGAAT) in the FEM1B gene increases insulin secretion and insulin resistance in mice, and the result is ovarian hyperandrogenism that occurs at the time of puberty in polycystic ovary syndrome (PCOS)." (PMID 31083386, 2019).
Angelman-like syndrome (1 paper, 2022). "For instance, FEM1B gain-of-function mutation, which cause a persistent activation of the reductive stress response, elicit developmental syndromes with some similarities to the HERC2 Angelman-like syndrome." (PMID 36241744, 2022).
Autoimmunity (1 paper, 2025). The occurrence of an immune reaction against the organism's own cells or tissues. "The degradation of TRAF2, facilitated by FEM1B, plays a crucial role in moderating excessive immune responses, thereby helping to prevent autoimmunity." (PMID 40392678, 2025).
colorectal cancer (1 paper, 2025). A primary or metastatic malignant neoplasm that affects the colon or rectum. "FEM1B is recognized for its significant pro‐apoptotic function in colorectal cancer; however, its influence and mechanisms regarding apoptosis in immune cells remain inadequately elucidated." (PMID 40392678, 2025).
developmental delay (1 paper, 2023). "Finally, FEM1B mutations are associated with developmental delay and intellectual disability." (PMID 37735597, 2023).
glioma (1 paper, 2021). A benign or malignant brain and spinal cord tumor that arises from glial cells (astrocytes, oligodendrocytes, ependymal cells). "We investigated the differential expression profile of lncRNAs in glioma and discovered that the lncRNA NKX3-1 plays an important role in cancer promotion via the Fem1b/SPDEF pathway." (PMID 34350121, 2021).
lentivirus infection (1 paper, 2025). Virus diseases caused by the Lentivirus genus. "Similarly, we found that Mettl3 knockdown by lentivirus infection markedly upregulated Fem1b mRNA level." (PMID 40016417, 2025).
cancer (4 papers, 2013 to 2024). A tumor composed of atypical neoplastic, often pleomorphic cells that invade other tissues. "In support of this, we observed a positive correlation between FEM1B expression and survival in certain cancer patients." (PMID 39140134, 2024). "Together, these observations demonstrate a role of FEM1B levels in cancer progression." (PMID 39140134, 2024). "We generated human cancer cell lines that lack SCR of FEM1B by genome editing." (PMID 39140134, 2024). "Therefore, we propose that FEM1B and SLBP levels can potentially be used as markers to predict the prognosis of certain cancers." (PMID 39140134, 2024).
tumor (4 papers, 2015 to 2024). "We investigated the physiological significance of SCR of FEM1B using xenograft tumour model in athymic nude mice." (PMID 39140134, 2024). "Although these analyses are based on mRNA expression, they indicate the clinical significance of FEM1B and SLBP protein levels in tumour progression, which can be regulated by SCR." (PMID 39140134, 2024). "Specifically, we show that LINC00174 favors the expression of SYBU, FEM1B, and SCD5 genes by sponging miR-145-5p, a well-known tumor suppressor microRNA downregulated in a variety of tumors, included TETs." (PMID 33161413, 2020).
FEM1B also shares sentences with these, for which no sentence is quoted: neurodevelopmental disorder (2 papers); autism (1); cervical cancer (1); cholangiocarcinoma (1); hepatocellular carcinoma (1); Insulin resistance (1); lung carcinoma (1); neuroblastoma (1); Ovarian Hyperandrogenism (1); Talipes equinovarus (1); thymoma (1).